OST4 (oligosaccharyltransferase complex subunit 4, non-catalytic)
Description:
Subunit of the oligosaccharyl transferase (OST) complex that catalyzes the initial transfer of a defined glycan (Glc(3)Man(9)GlcNAc(2) in eukaryotes) from the lipid carrier dolichol-pyrophosphate to an asparagine residue within an Asn-X-Ser/Thr consensus motif in nascent polypeptide chains, the first step in protein N-glycosylation. N-glycosylation occurs cotranslationally and the complex associates with the Sec61 complex at the channel-forming translocon complex that mediates protein translocation across the endoplasmic reticulum (ER). All subunits are required for a maximal enzyme activity. Specifically involved in maintaining stability of STT3A-containing OST complexes.
Tractability: Small molecule: a structure with a bound ligand is known. Antibody: UniProt predicts a signal peptide or a membrane-spanning region.
Gene: Protein-coding gene on chromosome 2 (27,070,470 to 27,071,685, reverse strand). Ensembl gene ENSG00000228474.
Subcellular location: Endoplasmic reticulum; Endoplasmic reticulum membrane
Pathways (Reactome):
Disease: Maturation of DENV proteins; Maturation of spike protein
Cell-Cell communication: Regulation of CDH1 posttranslational processing and trafficking to plasma membrane
Immune System: PD-L1(CD274) glycosylation and translocation to plasma membrane
Metabolism of proteins: Asparagine N-linked glycosylation
Gene Ontology:
Molecular function: protein binding
Biological process: protein N-linked glycosylation
Cellular component: oligosaccharyltransferase complex; oligosaccharyltransferase complex A; oligosaccharyltransferase complex B; endoplasmic reticulum membrane; endoplasmic reticulum
Genetic constraint (gnomAD): Loss-of-function variants: 3 observed, 2.25 expected, observed/expected ratio (o/e) 1.33, 90% interval 0.53 to 1.92. That is too few expected variants to judge how well the gene tolerates losing a copy. Missense variants: 52 observed, 50.78 expected, observed/expected ratio (o/e) 1.02, 90% interval 0.82 to 1.29. Synonymous variants: 23 observed, 22.35 expected, observed/expected ratio (o/e) 1.03, 90% interval 0.74 to 1.46.
Homologues: Orthologues: chimpanzee OST4 (100% identical), guinea pig OST4 (100% identical), macaque OST4 (100% identical), mouse Ost4 (100% identical), pig OST4 (100% identical), rat Ost4 (100% identical), zebrafish ost4 (95% identical).
Diseases named in the same sentence as OST4 in open-access papers:
OST4 is named in the same sentence as 3 diseases in open-access papers, as found by Europe PMC text mining. Sharing a sentence is not in itself a finding about the gene and the disease. The quoted sentences say what the papers report.
breast carcinoma (1 paper, 2017). "We selected four genes (NOP10, OST4, SNRPG, TOMM7) known to be present in EVs from MCF-7 breast cancer cells overexpressing Rab27b-GFP11." (PMID 28577337, 2017).
OST4 also shares sentences with these, for which no sentence is quoted: influenza infection (1 paper); myocarditis (1).